RNU6-366P (RNA, U6 small nuclear 366, pseudogene)
Gene: Small nuclear RNA gene on chromosome 14 (92,265,702 to 92,265,807, forward strand). Ensembl gene ENSG00000201097.
Homologues: Orthologues: chimpanzee U6 (100% identical), mouse Gm26122 (63% identical), rat LOC120094865 (59% identical). Paralogues in human: RNU6-921P (80% identical), RNU6-1152P (79% identical), RNU6-15P (79% identical), RNU6-211P (79% identical), RNU6-10P (78% identical), RNU6-16P (78% identical), RNU6-1 (77% identical), RNU6-116P (77% identical), RNU6-196P (77% identical), RNU6-2 (77% identical), RNU6-30P (77% identical), RNU6-3P (77% identical), and 1286 more.